S100A7 (S100 calcium binding protein A7)
Diseases named in the same sentence as S100A7 in open-access papers (continued):
Sharing a sentence is not in itself a finding about the gene and the disease.
breast carcinoma (continued). "Previous studies had confirmed that S100A7 expression could facilitate the infiltration of tumor-associated macrophages through multiple mechanisms in breast cancer, for example, it facilitated the infiltration of CD163-positive tumor-associated macrophages through activation of cPLA2." (PMID 38499391, 2024). "Moreover, increased NF-κB activity was observed in S100A7-overexpressing breast cancer cells, associated with evaluated levels of NF-κB target genes matrix metalloproteinase 9 (MMP9) and vascular endothelial growth factor (VEGF), resulting in proliferation and invasion." (PMID 32722137, 2020). "The wound healing assay further showed that S100A7 knockdown inhibited the migration of breast cancer cells after Taxol treatment, indicating that S100A7 contributed to chemotherapy resistance in breast cancer." (PMID 38499391, 2024). "The potential functions of S100A7 and its influence on chemotherapy sensitivity in breast cancer were elucidated using reverse transcription-quantitative PCR, Cell Counting Kit-8 (CCK-8) assay, Transwell assay, and wound healing assay." (PMID 38499391, 2024). "We performed enrichment analyses to investigate the potential pathways affected by S100A7 pan-cancer and in breast cancer." (PMID 38499391, 2024). "In this study, we showed that S100A7 promoted the proliferation, migration, and invasion of breast cancer cells, which is consistent with the results reported in other types of cancer." (PMID 38499391, 2024). "S100A7 was found to be closely related to various tumors, such as oral squamous cell carcinoma, breast cancer, prostate cancer, osteosarcoma, head and neck cancer, lung cancer, and ovarian cancer." (PMID 38499391, 2024). "The immune, stromal, and ESTIMATE scores were also related to S100A7 expression pan-cancer as well as in breast cancer." (PMID 38499391, 2024). "In breast cancer, the tumor heterogeneity indicators that most correlated with S100A7 expression were HRD, TMB, and LOH." (PMID 38499391, 2024). "Through in vitro experiments, we found that the IC50 of breast cancer cells to Taxol decreased when S100A7 was knocked down, indicating that S100A7 was indeed closely related to chemotherapy resistance in breast cancer." (PMID 38499391, 2024). "The CCK8 assay showed that the IC50 of breast cancer cells to Taxol diminished when S100A7 was knocked down." (PMID 38499391, 2024). "The KM plotter analysis revealed that higher expression of the S100A7 gene had a significantly poor overall survival probability among basal intrinsic subtype of breast cancer subjects." (PMID 33969603, 2022). "In our previous study, we have shown that S100A7 mediates its effect by directly binding to the RAGE receptor in breast cancer cells." (PMID 35135586, 2022). "In our present study, Kaplan-Meier (KM) plotter analysis revealed that high co-expression of both S100A7 and cPLA2 correlates with decreased overall survival of breast cancer patients." (PMID 35135586, 2022). "In invasive breast cancer cells, RAGE interaction with S100A7 mediates oncogenic response; in vitro, LPS treatment of S100A7 rose in a breast cancer cell line (MDA-MB-231)." (PMID 36613714, 2022). "Previously, our laboratory has shown that S100A7 mediates its oncogenic effects by directly binding to RAGE in invasive breast cancer cells." (PMID 33969603, 2022). "RAGE and S100A7 interaction were discovered to be involved in breast cancer and human cervical cancer through upregulation of ERK, MMP9, and NF-κB in vivo and in vitro investigations." (PMID 36613714, 2022). "We observed that only the basal subtype of breast cancer showed significantly high levels of S100A7 (p-value = 1.81e-22) and PLA2G4A (p-value = 1.45e-54) as compared to normal subjects." (PMID 35135586, 2022). "The chromosomal copy number amplification at 1q21.3, where S100A7 is located, serves as a trackable biomarker in cell-free DNA and a therapeutic target for breast cancer." (PMID 35205150, 2022).
breast carcinoma (continued). "S100A7 has been described in breast cancer but the present study is the first to highlight a potential link between S100A7 and endometriosis." (PMID 35204508, 2022). "In vitro, treatment of LPS on an S100A7 overexcited in breast cancer cell line (MDA-MB-231), and in vivo treatment of MVT-1 (mouse mammary tumor cell line) with mS100A7/A15 revealed enhanced RAGE manifestation in a dose-dependent and time-dependent manner." (PMID 36613714, 2022). "As we have shown that the expression of S100A7 and LPS level increases along with an increase in tumor burden, we elucidated the effect of LPS treatment on S100A7 in breast cancer." (PMID 33969603, 2022). "It is reported that LPS from the commensal microbiota of the human breast induced the expression of S100A7 in breast cancer cells." (PMID 35498722, 2022). "Analysis of human breast cancer samples also highlighted the inverse correlation between S100A7 and TLR4 expression." (PMID 33969603, 2022). "We discovered that S100A7 showed a significant positive correlation with PLA2G4A in breast cancer patients, mainly in breast invasive carcinoma." (PMID 35135586, 2022). "(b) LPS increases S100A7 expression in breast cancer cells that regulate TLR4 and RAGE expression and modulate breast tumorigenesis." (PMID 33969603, 2022). "We also discovered that cPLA2 knockdown in S100A7 expressing breast cancer cells significantly reduced the PGE2 level." (PMID 35135586, 2022). "Human breast cancer tissue and plasma samples were used to analyze the expression of S100A7, cPLA2, and PGE2." (PMID 35135586, 2022). "Our results revealed that LPS treatment increased the expression of S100A7 protein in breast cancer cells (SUM159)." (PMID 33969603, 2022). "This is the first study, which reports that LPS increases S100A7 expression in breast cancer cells, which in turn attenuates the expression of TLR4." (PMID 33969603, 2022). "S100A7 is a microbicidal protein, and previous reports from our laboratory have established its role in breast cancer progression and metastasis." (PMID 33969603, 2022). "In the present study, we performed an in-depth analysis of S100A7 and cPLA2 in breast cancer progression and metastasis using multiple breast cancer cell lines and patient samples." (PMID 35135586, 2022). "For this, we analyzed the differential expression of S100A7 and cPLA2 genes across different stages, grades, and tumor sizes of breast cancer patients using publically available Caldas and Chin datasets." (PMID 35135586, 2022). "According to the latest in vitro studies in breast cancer cells, LPS increases the expression of S100A7, which inhibits TLR4 and promotes RAGE accumulation in breast carcinogenesis." (PMID 36613714, 2022). "S100A7-overexpressing or downregulated human metastatic breast cancer cells were used to evaluate the S100A7-mediated downstream signaling mechanisms." (PMID 35135586, 2022). "Overall, our data suggest that cPLA2 inhibition suppressed S100A7-induced PGE2 generation by breast cancer cells." (PMID 35135586, 2022). "According to recent in vitro studies in breast cancer cells, LPS increases the expression of S100A7, which inhibits TLR4 and promotes RAGE accumulation in breast carcinogenesis." (PMID 36613714, 2022). "This study shows that exposing HMECs to fluid flow upregulates genes identified clinically to be overexpressed during breast cancer development, including S100A7 and S100P." (PMID 35087607, 2022). "We discovered that the level of both S100A7/PGE2 was significantly higher in breast cancer patients as compared to normal subjects." (PMID 35135586, 2022). "Next, we explored the downstream mechanistic pathway regulated by the S100A7/cPLA2 axis in metastatic breast cancer cells." (PMID 35135586, 2022). "Our comprehensive studies using in-vitro assays, in-vivo mouse models, and patient samples showed that a novel cross-talk between S100A7 and cPLA2 enhances breast cancer growth and metastasis." (PMID 35135586, 2022).
breast carcinoma (continued). "We observed overexpression of S100P in patients with all subtypes of breast cancer and overexpression of S100A7 in patients with luminal B, HER2 positive and basal breast cancer." (PMID 35087607, 2022). "We have shown that S100A7/RAGE signaling mediates its oncogenic effect by activating the NF‐κB in breast cancer cells." (PMID 33969603, 2022). "The treatment of breast cancer cells with LPS increased the expression of S100A7 in breast cancer cells in vitro." (PMID 33969603, 2022). "Next, we evaluated the correlation between S100A7 and cPLA2 at the protein level using the same breast cancer patient samples." (PMID 35135586, 2022). "Here, we demonstrate that the S100A7/RAGE axis enhances cPLA2 expression in metastatic breast cancer cells." (PMID 35135586, 2022). "In this study, we found that S100A7 and cPLA2 are highly expressed and correlate with decreased overall survival in breast cancer patients." (PMID 35135586, 2022). "A higher level of S100A7 total protein was observed in the primary tissues of breast cancer, LUAD and LUSC compared to normal tissues, according to the immunohistochemistry results of the HPA dataset." (PMID 35205150, 2022). "We also observed that poorly differentiated high-grade breast tumors expressed a high level of both S100A7 and cPLA2 as compared to well-differentiated mammary tumors and their adjacent normal tissues." (PMID 35135586, 2022). "Altogether, our in-vivo studies suggest that cPLA2 inhibition tends to be a promising strategy against S100A7 overexpressing metastatic mammary tumors." (PMID 35135586, 2022). "In recent years, a number of studies demonstrated that the dysregulation of S100A7 was a common feature in various cancer cells, especially in breast cancer, oral squamous cell carcinoma, gastric cancer, and lung cancer." (PMID 34323409, 2021). "For example, JAB1 interacts with S100A7 to promote cell survival through the enhancement of NF-κB and Akt activities in breast cancer cells." (PMID 34244488, 2021). "In breast cancer cells, intracellular S100A7 was shown to form a complex with the cofactor Jab1, resulting in the translocation of Jab1 to the nucleus and its interaction with HIF-1a, resulting in the transcription of HIF-1a dependent genes." (PMID 34360919, 2021). "In ER+ breast cancer, S100A7 limits the proliferation and motility of tumor cells by downregulating the β-catenin/TCF4 pathway." (PMID 32728097, 2020). "The top gene was S100A7, which has been found to be expressed in several tissues including breast adenocarcinomas and squamous carcinomas of the head and neck, the cervix, and the lung; S100A7 is also related survival of breast cancer patients." (PMID 31850079, 2019). "Stat3 phosphorylation activated Oncostatin M and the downstream S100A7 gene expression in breast cancer." (PMID 31731716, 2019). "RNA-seq results were confirmed by WB analysis of S100A7 in cells harvested from soft and stiff IPNs, IHC of S100A7 in breast cancer patient tissues, and qPCR of cells harvested from soft and stiff IPNs." (PMID 31015465, 2019). "Expression of S100A7 mRNA and protein is increased mainly in squamous cell carcinoma tissues and breast cancer." (PMID 29607329, 2018). "We also confirmed elevated S100A7 mRNA expression in primary breast tumor cells compared with the normal epithelial cells, both retrieved from frozen primary human breast cancer tissues with tumor infiltration into surrounding adipose tissues." (PMID 28629450, 2017). "The results of our study suggest that paracrine production of cytokines from ASCs stimulates breast carcinoma cell growth via upregulation of S100A7 expression in breast cancer cell lines." (PMID 28629450, 2017). "Mechanistically, S100A7 enhances survival of breast cancer cells by binding to c-Jun activation domain-binding protein 1 (Jab1) and increasing activity of NF-κB and p-Akt." (PMID 28212564, 2017).
breast carcinoma (continued). "For the purpose of the following experiments, S100A7 upregulation by coculture with murine ASCs was also confirmed in different types of breast cancer cell lines relative to that in the pre-3T3 or monoculture at mRNA and protein levels." (PMID 28629450, 2017). "Elevated expression levels of S100A7 then promote breast cancer malignancy via several signaling pathways, such as RAGE." (PMID 28629450, 2017). "Our results show that expression of RAGE was increased in breast cancer cells in correspondence with the elevated S100A7 expression by coculture with ASCs." (PMID 28629450, 2017). "Our mechanistic investigation has revealed that RAGE mediates its functional effects in breast cancer by binding to S100A7." (PMID 27014721, 2016). "This demonstrated that miR-29b functions downstream of S100A7 and is important in determining the differential effects of S100A7 in breast cancer cells." (PMID 25622979, 2015). "In the present article, we proposed a novel mechanism for the differential roles of the inflammatory protein S100A7 on the proliferation of ER− and ER+ breast cancer cells." (PMID 25622979, 2015). "It has been shown that S100A7 promotes cancer growth and metastasis in basal-like (ER−) breast cancer cells." (PMID 25622979, 2015). "To investigate the effect of S100A7 upregulation in human breast cancer, we generated a panel of S100A7 overexpressing breast cancer cell lines." (PMID 25622979, 2015). "In this work, ER status was used as the primary standard for dividing breast cancer cells into two groups with distinct responses to S100A7." (PMID 25622979, 2015). "Accordingly, S100A7 upregulation correlates with poor prognosis for patients with basal subtype breast carcinoma." (PMID 25622979, 2015). "In conclusion, we report a novel regulatory route that determines the pro-/anti-proliferative roles of S100A7 in ER− and ER+ breast cancer." (PMID 25622979, 2015). "In this study, we characterized the tumor-enhancing effects of S100A7 in MDA-MB-468 breast cancer cells." (PMID 23618129, 2013). "S100A7 is among the most highly expressed genes in preinvasive breast cancer, is a marker of poor survival when expressed in invasive disease, and promotes breast tumor progression in experimental models." (PMID 23618129, 2013). "Both S100A15 (also called S100A7A) and S100A7 proteins have been demonstrated to be distinctly expressed in normal breast tissue and breast cancer." (PMID 23451142, 2013). "Although a number of putative functions have been proposed for S100A7, its biological role, particularly in breast cancer, remains to be defined." (PMID 23618129, 2013). "In breast cancer cell lines, IFNγ down-regulates S100A7 expression, through STAT1 transcriptional activity." (PMID 23285311, 2012). "Increased S100A7 expression has been reported in several epithelial malignancies such as, in situ ductal breast carcinoma, lung, bladder, skin, esophageal and gastric cancer." (PMID 20689826, 2010). "Precursor osteoclasts, prepared from bone marrow cultures, were placed in 24-well plates and inserts containing vector control or S100A7-shRNA-downregulated breast cancer cells (5×104 cells) were placed in the wells." (PMID 18320059, 2008).
breast carcinoma (continued). "Human osteoclast precursors, isolated from mouse bone marrow, were differentiated into TRAP+ multinucleated cells, which were larger in size and number in the S100A7-control breast cancer cells as compared to the S100A7-downregulated cells in transwell assays." (PMID 18320059, 2008). "We have seen increased expression of S100A7 in two breast cancer cell lines following EGF stimulation." (PMID 18320059, 2008). "Univariate analysis showed that SBEM was strongly associated with psoriasin/S100A7 and less so with HER-2, the latter being well documented to confer poor prognosis in breast cancer patients." (PMID 18269587, 2008). "S100A7 has been shown to be overexpressed in breast cancers at sites of necrosis in tumor tissues, as well as in the nasal fluid during allergic inflammatory reactions." (PMID 18320059, 2008). "This is a novel report on the role of S100A7 in EGF-induced signaling in breast cancer cells and in osteoclast formation." (PMID 18320059, 2008). "Although S100A7 has been reported to play a role in breast cancer, the molecular mechanisms of its effects are not well known." (PMID 18320059, 2008). "We found that S100A7-downregulated breast cancer cells exhibited a reduction in EGF-induced chemotaxis and invasion on matrigel-coated transwells." (PMID 18320059, 2008). "This was of interest since we and others have previously found that human psoriasin/S100A7 expression is highly up-regulated in human breast cancer compared to normal breast tissue." (PMID 15717926, 2005). "Finally, in vitro experiments were performed to validate the potential function of S100A7 in breast cancer." (PMID 38499391, 2024). "Furthermore, by binding to RAGE, the proinflammatory ligand S100A7 induces breast cancer growth and metastasis leading to ERK, NF-kB activation and cell migration." (PMID 39830522, 2024). "In breast cancer, DMPss and EREG-EXPss were associated with S100A7 expression." (PMID 38499391, 2024). "Additionally, lipopolysaccharide (LPS), derived from the breast tumor microbiota, was found to increase S100A7 expression in breast cancer cells in vitro." (PMID 39830522, 2024). "Finally, we confirmed the potential functions of S100A7 and examined its influence on chemosensitivity using an in vitro breast cancer cell model." (PMID 38499391, 2024). "In addition, we discovered that S100A7 expression strongly correlated with cPLA2 expression in metastatic breast cancer patients." (PMID 35135586, 2022). "S100A7, a pro-inflammatory molecule has been shown to enhance breast cancer growth and metastasis." (PMID 35135586, 2022). "However, the crosstalk between S100A7 and cPLA2 in regulating aggressive breast cancer growth and metastasis and its downstream effects in iTME are not known." (PMID 35135586, 2022). "Moreover, via the Kaplan–Meier plotter tool, we analyzed the survival data and demonstrated an association between a high level of S100A7 and poor OS, distant metastasis-free survival (DMFS) and postprogression survival (PPS) prognosis for breast cancer." (PMID 35205150, 2022). "Moreover, our TMA analysis highlighted the inverse correlation of S100A7 with TLR4 expression in breast cancer patients." (PMID 33969603, 2022). "We first evaluated the protein expression of S100A7 in LPS‐treated breast cancer cells." (PMID 33969603, 2022). "In addition, the coexpression of S100A7 and cPLA2 with poor overall survival for breast cancer patients, especially in aggressive IM and basal-like TNBC." (PMID 35135586, 2022). "Interestingly, we also found that inhibition of S100A7/cPLA2 signaling reduced PGE2 level in S100A7 overexpressing pre-clinical breast cancer mouse model." (PMID 35135586, 2022). "Furthermore, BMDMs were treated with EP4 inhibitor or incubated with conditioned media of AACOCF3 treated S100A7 expressing breast cancer cells." (PMID 35135586, 2022). "S100A7 mediates breast cancer growth by enhancing inflammatory signaling cascades." (PMID 35135586, 2022).